RN7SL756P (RNA, 7SL, cytoplasmic 756, pseudogene)
Gene: Miscellaneous RNA gene on chromosome 17 (67,457,023 to 67,457,290, reverse strand). Ensembl gene ENSG00000244610.
Homologues: Orthologues: chimpanzee Metazoa_SRP (99% identical), guinea pig Metazoa_SRP (55% identical). Paralogues in human: RN7SL2 (81% identical), RN7SL1 (81% identical), RN7SL3 (80% identical), RN7SL230P (79% identical), RN7SL357P (79% identical), RN7SL75P (78% identical), RN7SL296P (78% identical), RN7SL326P (78% identical), RN7SL164P (77% identical), RN7SL448P (77% identical), RN7SL478P (77% identical), RN7SL575P (77% identical), and 698 more.